AFG3L2 (AFG3 like matrix AAA peptidase subunit 2)
Diseases named in the same sentence as AFG3L2 in open-access papers (continued):
Sharing a sentence is not in itself a finding about the gene and the disease.
neurological disorders (6 papers, 2011 to 2024). "Bergmann glial cell is an active participant involved in AFG3L2 deficiency-related neurological disorders." (PMID 38012514, 2024). "Mutations in AFG3L2 lead to diseases like slow progressive ataxia, which is a neurological disorder." (PMID 38012514, 2024). "m-AAA is encoded by AFG3L2, and AFG3L2 mutation or knockdown leads to unfolded mitochondrial protein accumulation and complex IV deficiency, resulting in respiratory deficiency mainly in neurological diseases." (PMID 35574326, 2022). "To explore how a deficiency of m‐AAA protease subunits affects astrocytes, we restricted our investigations to the cerebellum, which is the tissue most affected in human neurological disorders caused by AFG3L2 mutations." (PMID 30989755, 2019). "The m‐AAA protease plays crucial roles to maintain mitochondrial homeostasis in neurons, as underlined by the spectrum of neurological diseases associated with mutations in genes encoding the individual subunits SPG7 and AFG3L2." (PMID 30989755, 2019). "In conclusion, we propose a revised model for the pathogenesis of neurological diseases linked to Afg3l2 deficiency, in which astrocytes are not innocent bystanders, but they actively amplify and precipitate neuronal damage, by assuming a reactive status and impairing glutamate uptake." (PMID 30989755, 2019).
cancer (2 papers, 2021 to 2024). A tumor composed of atypical neoplastic, often pleomorphic cells that invade other tissues. "For example, mechanisms of AFG3L2 and SLC25A39 regulation was just elucidated over the past few years, and it would not be surprising to see these genes upregulated or mutated in cancers to bypass increased oxidative stress at the mitochondria." (PMID 39188677, 2024).
infection (2 papers, 2025 to 2026). The state of being infected such as from the introduction of a foreign agent such as serum, vaccine, antigenic substance or organism. "Additionally, compared to AFG3L2-deficient cells, cells reconstituted with wild-type AFG3L2 but not the protease-inactive AFG3L2E575Q mutant inhibited SeV-induced transcription of IFNB1 and IFI44 genes at 8 h post-infection." (PMID 41599057, 2026). "Consistently, comparing to AFG3L2-deficient cells, cells reconstituted with wild-type AFG3L2 but not the protease-inactive AFG3L2E575Q mutant down-regulated VISA level in uninfected and SeV-infected cells, and inhibited SeV-induced phosphorylation of TBK1S172 and IRF3S386 at 6 h post-infection." (PMID 41599057, 2026). "Additionally, we show that the natural compound physalin F promotes AFG3L2 proteolytic activity to regulate the degradation of VISA and suppress innate antiviral response, offering a promising therapeutic approach to disorders associated with infection of the RNA virus and AFG3L2 dysfunctions." (PMID 41599057, 2026). "In these experiments, reconstitution of AFG3L2 had no marked effects on VISA level and SeV-induced phosphorylation of TBK1S172 and IRF3S386 at 12 h post-infection." (PMID 41599057, 2026).
tumor (2 papers, 2025 to 2026). "Moreover, whereas AFG3L2 overexpression blocked these effects, overexpression of AFG3L2(Δm‐AAA) markedly aggravated tumor growth." (PMID 40305785, 2025).
autosomal dominant disease (1 paper, 2023). Autosomal dominant form of disease. "Other homohexameric ATPases, such as VPS4A and AFG3L2, have been identified to cause autosomal dominant diseases through a dominant negative mechanism." (PMID 36645181, 2023).
mitochondrial disease (1 paper, 2024). "This further corroborates the potential of AFG3L2 as a prognostic and/or diagnostic marker for various mitochondrial diseases and neurodegenerative disorders related to aging." (PMID 38012514, 2024). "This study emphasizes that this AFG3L2 mutation can be added as a genetic marker along with neuroradiological and biochemical spectrum for a rare mitochondrial disease with neurodegenerative phenotype." (PMID 38012514, 2024).
AFG3L2 also shares sentences with these, for which no sentence is quoted: Ataxia (10 papers); cerebellar ataxia (2); Friedreich ataxia (2); progressive external ophthalmoplegia (2); acute lymphoblastic leukemia (1); acute myeloid leukemia (1); amyotrophic lateral sclerosis (1); bipolar disorder (1); Blindness (1); cerebellar disorder (1); chronic myelogenous leukemia (1); congenital stationary night blindness (1); Creutzfeldt-Jakob disease (1); dentatorubral-pallidoluysian atrophy (1); dilated cardiomyopathy (1); frontotemporal dementia (1); Gait ataxia (1); heart failure (1); hypomyelinating leukodystrophy (1); Kohlschutter’s syndrome (1); leukemia (1); motor neuron disorder (1); myoclonic epilepsy (1); myopathy (1); Oculomotor apraxia (1); ophthalmoplegia (1); Parkinsonism (1); peripheral neuropathy (1); PHARC syndrome (1); prostate carcinoma (1).
A further 4 diseases each share a sentence with AFG3L2 in 1 paper.